NLRP3 (NLR family pyrin domain containing 3)
Diseases named in the same sentence as NLRP3 in open-access papers (continued):
Sharing a sentence is not in itself a finding about the gene and the disease.
atherosclerosis (continued). "NLRP3 inflammasome is involved in the molecular etiology of atherosclerosis and heart failure." (PMID 32358544, 2020). "Conversely, Nlrp3 knockout alleviated the C. pneumoniae‐accelerated atherosclerosis." (PMID 32508013, 2020). "Based on these data, we speculate that fucoidan can activate autophagy, resulting in the inhibition of NLRP3 inflammasome activity in atherosclerosis." (PMID 33505579, 2020). "The NLRP3 protein is the main functional component of inflammasomes, which has been discovered to mediate a wide variety of diseases, such as diabetes, gouty arthritis, microbial infection, atherosclerosis, and non-alcoholic steatohepatitis." (PMID 32117956, 2020). "Several studies implicate the NLRP3 inflammasome in the pathogenesis of atherosclerosis." (PMID 32596261, 2020). "Based on these previous findings, we speculated that Tan IIA may inhibit the NLRP3 inflammasome activation and thereby prevents the development of atherosclerosis." (PMID 33290264, 2020). "13-MB negatively modulates the NLRP3 inflammasome and may be a therapeutic target for atherosclerosis." (PMID 31993073, 2020). "Inhibition of UA-induced NLRP3 inflammasome activation may be a new therapeutic target for atherosclerosis." (PMID 33304270, 2020). "Indeed, other research groups and our team have proved that NLRP3 inflammasome plays crucial roles in several kinds of diseases, including cancer, type 2 diabetes mellitus, atherosclerosis, and heart disease." (PMID 33100331, 2020). "Thus, the role of the NLRP3 inflammasome in the pathogenesis of atherosclerosis warrants further investigations." (PMID 32751530, 2020). "CoQ10 could also inhibit the inflammatory proteins such as IL-6, TNF-α, ICAM-1, VCAM-1 and NLRP3, thus exerting the role inhibiting atherosclerosis." (PMID 32792941, 2020). "Thus, the NLRP3 inflammasome probably fuels inflammation in the context of COVID-19 to promote the progression of atherosclerosis." (PMID 33553222, 2020). "Through animal experiments, it was concluded that dietary PUFAs could reduce atherosclerosis by activating macrophage autophagy and inhibiting the activation of the NLRP3 inflammasome." (PMID 32328119, 2020). "Indeed, the aberrant activation of the NLRP3 inflammasome has been shown to drive numerous chronic inflammatory diseases including atherosclerosis, gout, rheumatoid arthritis, ischemic stroke, and many more." (PMID 33036374, 2020). "For example, NLRP3 inflammasome is a crucial mediator for WD-induced trained immunity that could potentially promote atherosclerosis, but it can also drive atherosclerosis development in a trained-immunity-independent manner." (PMID 32153588, 2020). "Numerous studies demonstrate that the activation of NLRP3 inflammasome plays a crucial role in the occurrence of cardiovascular disorders, such as atherosclerosis, hypertension, myocardial ischemia, cardiomyopathy, infectious cardiac disease, and heart failure." (PMID 32581721, 2020). "As active IL-1α can be produced in the absence of the NLRP3 inflammasome through calpain-mediated processing, deficiency of the NLRP3 inflammasome would not impair the development of atherosclerosis." (PMID 31354731, 2019). "Further studies in similar mouse models as well showed decreased severity of atherosclerosis in mice lacking NLRP3, caspase-1 or IL-1β, while in another study NLRP3 inflammasomes were not critically implicated in atherosclerosis progression." (PMID 31795299, 2019). "As evidence emerges supporting the role of NLRP3 in the pathogenesis of atherosclerosis, targeting the inflammasome becomes an attractive therapeutic approach, where miRNAs could be suitable novel tools." (PMID 31118894, 2019). "Moreover, cholesterol crystals and oxidized LDL particles have been shown to activate the NLRP3 inflammasome, which leads to a vascular response during atherosclerosis progression." (PMID 31582899, 2019).
atherosclerosis (continued). "SFA or cholesterol loading of macrophages is known to induce robust ER stress and mitochondrial oxidative stress, upstream of NLRP3 inflammasome activation and IL-1β and IL-18 secretion, resulting in an inflammatory response that drives atherosclerosis progression." (PMID 31422082, 2019). "In addition, increasing evidence highlights that both ER stress and NLRP3 inflammasome activation contribute to atherosclerosis (AS)." (PMID 31687078, 2019). "It has been recently reported that both IL-1β maturation and its release are tightly regulated by NLRP3 inflammasome, which has been involved in several systemic inflammatory diseases such as gout, atherosclerosis, pulmonary fibrosis and contact hypersensitivity." (PMID 29434227, 2018). "A plethora of information, resulting from the analysis of rodent and human atherosclerotic plaques, has demonstrated that IL-1β and IL-18, both of which are products of the NLRP3 inflammasome activation, play a key role in the initiation and progression of atherosclerosis." (PMID 29515457, 2018). "Silencing of NLRP3 impeded atherosclerosis progression and stabilized atherosclerotic plaques." (PMID 29773990, 2018). "Therefore, the NLRP3 inflammasome plays an important role in the inflammatory process of atherosclerosis." (PMID 29850543, 2018). "Inflammasomes, mainly the NLRP3 inflammasome, play a role in inflammatory processes, many diseases and metabolic states, including Multiple Sclerosis, Alzheimer’s disease, Parkinson’s disease, atherosclerosis, type 2 diabetes, and obesity." (PMID 29491864, 2018). "Interestingly, some human VSMCs (hVSMCs) express components of the NLRP3 inflammasome at the site of atherosclerosis, and hVSMCs themselves can contribute to local inflammation." (PMID 30136196, 2018). "Interestingly, examination of the role of NLRP3 inflammasomes in the ApoE KO mouse model of atherosclerosis has however yielded contradictory results." (PMID 29515457, 2018). "All these studies highlight NLRP3 as a potential therapeutic target for atherosclerosis." (PMID 30405440, 2018). "Activated NLRP3 inflammasomes exacerbate macrophage lipid deposition and atherosclerosis." (PMID 29773990, 2018). "The NLRP3 inflammasome, therefore, appears to warrant further investigation as a potential target for inflamm-aging related to atherosclerosis given that such mechanisms are now of well known importance in atherosclerosis." (PMID 29686666, 2018). "The NLRP3 inflammasome is reported to recognize multiple endogenous danger signals and trigger the release of proinflammatory cytokines including active IL-1β, thus contributing to many diseases such as atherosclerosis and T2 diabetes." (PMID 29854830, 2018). "Indeed, we and others have revealed a pivotal role of NLRP3 inflammasomes in the development of cardiovascular and renal diseases including atherosclerosis." (PMID 29259717, 2017). "Dietary PUFAs reduce atherosclerosis and macrophage inflammation, but how nucleotide-binding oligomerization domain leucine-rich repeat-containing receptor protein (NLRP3) inflammasome activation and autophagy influence PUFA-mediated atheroprotection is poorly understood." (PMID 28729463, 2017). "The regulatory mechanisms of NLRP3 inflammasomes may be a potential target for multiple inflammatory diseases including atherosclerosis." (PMID 29259717, 2017). "Our findings may suggest a role for IL-27 in clinical atherosclerosis, at least partly through its enhancing effects on LPS-mediated functions and NLRP3 inflammasome activation." (PMID 29176764, 2017). "NLRP3 is a receptor important for host responses to infection, yet is also known to contribute to devastating diseases such as Alzheimer's disease, diabetes, atherosclerosis, and others, making inhibitors for NLRP3 sought after." (PMID 28943355, 2017).
atherosclerosis (continued). "Our results suggest that dietary n-3 (FO and EO) and n-6 PUFAs (BO) markedly enhance activation of macrophage autophagy, improve mitochondrial function, and attenuate NLRP3 inflammasome activation, all of which partially explain their protective effects against atherosclerosis." (PMID 28729463, 2017). "NOD-, LRR-, and pyrin domain-containing 3 (NLRP3) is widely recognized as having a central role in various sterile inflammatory processes and conditions, including trauma/hemorrhage, gout, tissue necrosis, Alzheimer’s, atherosclerosis, and renal IR." (PMID 29163464, 2017). "Lastly, mice with NLRP3 or IL-1β deficiency in bone marrow cells develop less inflammation and atherosclerosis under hypercholesterolemic conditions, supporting the correlation between activation of the NLRP3 inflammasome in macrophages and development of atherosclerosis." (PMID 28729463, 2017). "Therefore, the regulatory mechanisms of NLRP3 inflammasomes are regarded as potential targets for atherosclerosis treatment." (PMID 29259717, 2017). "Emerging evidence suggests that NLRP3 activation is involved in inflammatory responses, antimicrobial responses, and various human diseases, including autoimmune inflammatory disease, Alzheimer’s disease, atherosclerosis, and type 2 diabetes." (PMID 29258239, 2017). "NLRP3-mediated inflammatory response is involved in atherosclerosis and the development of ischemic stroke, and regulation of NLRP3 inflammasome activation may play a critical role in the prevention and treatment of ischemic stroke." (PMID 27589720, 2016). "The NLRP3 inflammasome recognizes many endogenous materials as danger signals and triggers the release of strong pro-inflammatory cytokines including active IL-1β, thus contributing to diverse diseases as atherosclerosis, Alzheimer’s disease, and T2 diabetes." (PMID 27965665, 2016). "Indeed, activation of NLRP3 inflammasome in macrophages has been involved in the cholesterol crystals formation in the pathogenesis of atherosclerosis." (PMID 28104929, 2016). "Additionally, 4 genes (Tnfsf15, Tlr3, Nlrp3, and Lepr), which have known roles in cholesterol efflux and atherosclerosis, were present in the network." (PMID 27239478, 2016). "This suggests that the high expression of P2X7R and NLRP3 in macrophages may be involved in the progression of atherosclerosis." (PMID 25761252, 2015). "Also, NLRP3−/− and ASC−/− animal models have shown the role of NLRP3 in the progression of atherosclerosis and myocardial dysfunction, although it has been questioned." (PMID 25788762, 2015). "We also tried to explore the mechanisms of the impact of NLRP3 inflammasome on atherosclerosis." (PMID 24999295, 2014). "Recent studies have shown that cholesterol crystal activate the NLRP3 inflammasome and release of IL-1β, which indicates that the NLRP3 inflammasome may have a role in the development of atherosclerosis." (PMID 24999295, 2014). "The importance of NLRP3/caspase-1 in atherosclerosis has been questioned." (PMID 24686534, 2014). "The aim of this study was to determine whether inhibition of NLRP3 signaling by lentivirus-mediated RNA interference could reduce atherosclerosis and stabilizes plaques." (PMID 24999295, 2014). "The role of the NLRP3 inflammasome in atherosclerosis remains controversial." (PMID 24999295, 2014). "However, the critical role of the NLRP3 inflammasome in atherosclerosis has been challenged by another study of double-mutant mice generated by crossing Apoe−/− mice with Nlrp3−/−, Pycard−/−, or Caspase1−/− mice." (PMID 24999295, 2014). "Our data showed that mRNA levels of ABCA1 and ABCG1 were increased after the treatment of NLRP3i, suggesting that NLRP3 gene silencing could be a potentially therapeutic mean to increase macrophage cholesterol efflux for the prevention of atherosclerosis." (PMID 24999295, 2014).
atherosclerosis (continued). "NLRP3 inflammasomes may play a vital role in atherosclerosis, and lentivirus-mediated NLRP3 silencing would be a new strategy to inhibit plaques progression and to reduce local inflammation." (PMID 24999295, 2014). "These preclinical studies provide biochemical evidence that the dysregulation of SIRT1-AMPK-SREBP pathway and stimulation of NLRP3 inflammasome and IL-1β production may coordinately contribute to the initiation and progression of atherosclerosis." (PMID 23825667, 2013). "Hence, there are numerous obesity-related diseases, which include cardiovascular disease, atherosclerosis, insulin resistance, and type 2 diabetes mellitus (T2DM), which are linked to the NLRP3 inflammasome." (PMID 24367371, 2013). "These translational studies provide in vivo evidence that the dysregulation of SIRT1-AMPK-SREBP and stimulation of NLRP3 inflammasome may contribute to vascular lipid deposition and inflammation in atherosclerosis." (PMID 23825667, 2013). "It remains unclear why these two different mouse models of atherosclerosis have produced opposite findings in regards to the role of the NLRP3-inflammasome in cardiovascular inflammation." (PMID 23087690, 2012). "For example, NLRP3 is activated by uric acid crystals, cholesterol crystals, amyloid crystals, as well as high glucose levels which render NLRP3 activation as a crucial element of a number of important inflammatory diseases such as gout, atherosclerosis, amyloidosis and diabetes." (PMID 22046355, 2011). "The NLRP3 inflammasome plays an essential role in immune defense against bacterial, fungal, and viral infections, but its dysregulation is involved in the pathogenesis of several inflammatory diseases, including atherosclerosis, thus contributing to its progression." (PMID 41590246, 2026). "Deficiency of each of the three inflammasome proteins (NLRP3, ASC, Caspase 1) has been shown to reduce atherosclerotic lesion or plaque size, and the inflammasome regulates the production and recruitment of monocytes through IL-1β in the early stages of atherosclerosis." (PMID 40956333, 2025). "Moreover, NLRP3 activation is linked to increased copper concentrations, suggesting that cuproptosis may trigger NLRP3 to advance atherosclerosis progression." (PMID 40861271, 2025). "At the molecular level, the formation of NLRP3 inflammatory vesicles in macrophages is a key step in the spread of inflammation, and the NLRP3/IL-1/IL-6/hypersensitive CRP (hs-CRP) classical inflammatory pathway is closely associated with the increased risk of atherosclerosis." (PMID 40182041, 2025). "The NLRP3 inflammasome is pivotal in the development of numerous diseases, spanning neurodegenerative conditions such as multiple sclerosis, Alzheimer’s, and Parkinson’s diseases, as well as metabolic disorders like atherosclerosis, type 2 diabetes, and obesity." (PMID 40083546, 2025). "ASC functions as an adaptor in inflammasome assembly, while NLRP3 acts as a sensor detecting diverse stimuli such as oxidative stress, mitochondrial damage, or crystal accumulation, commonly observed in heart diseases like atherosclerosis, heart failure, or myocardial infarction." (PMID 40149903, 2025). "Importantly, not all inflammasome activity is harmful: some studies suggest that complete NLRP3 deficiency does not always decrease atherosclerosis, possibly due to compensation by alternative inflammatory pathways." (PMID 40832143, 2025). "Moreover, the interaction between cholesterol crystals and complements may exert its effects by activating the NLRP3 inflammasome, thereby promoting the progression of atherosclerosis." (PMID 38704561, 2024). "Furthermore, our results may have significant therapeutic ramifications for the treatment of CAPS, sepsis, atherosclerosis, Parkinson’s disease, and many other diseases in which excessive NLRP3 inflammasome activation contributes to pathology." (PMID 38519142, 2024).
atherosclerosis (continued). "For example, miR-223 has been shown to target the NLRP3 inflammasome in the brain and reduce neuroinflammation and neuronal damage, inhibit NLRP3 expression, and reduce inflammation in various disease models, including arthritis, atherosclerosis, and myocardial infarction." (PMID 38892264, 2024). "It has been reported that inhibiting caspase 1 antagonizes NLRP3 inflammasome assembly, prevents foam cell formation and pyroptosis in macrophages, partly by boosting Parkin-mediated mitophagy and efferocytosis, and thereby ameliorates vascular inflammation and atherosclerosis." (PMID 38812059, 2024). "Consequently, we hypothesize that Corilagin can suppress the activation of NLRP3 inflammasome to alleviate atherosclerosis by disrupting the Olfr2 signaling pathway." (PMID 38803504, 2024). "Current research highlights the significant role of the NLRP3 inflammasome pathway in the pathogenesis of atherosclerotic conditions such as myocardial infarction and ischemic cerebral infarction, positioning it as a potential therapeutic target in atherosclerosis management." (PMID 39822376, 2024). "Notably, the clinical use of canakinumab, an anti-IL-1β agent, has shown significant promise, as it reduced the incidence of lung cancer in patients with atherosclerosis, providing a robust clinical validation of the critical role of NLRP3 and IL-1β in cancer pathophysiology." (PMID 39301197, 2024). "have revealed that olfactory receptor 2 (Olfr2) interacts with TLR4 in vascular macrophages leading to NLRP3 inflammasomes activation via adenylate cyclase 3 (Adcy3) to drive atherosclerosis development, provides a new target for the prevention and treatment of atherosclerosis." (PMID 38803504, 2024). "In contrast to complete inhibition of the NLRP3 inflammasome or its products, precise, selective inhibition of dyslipidemia-driven inflammasome activation in atherosclerosis may be less immunosuppressive, and, thus, clinically more acceptable as a therapeutic strategy to reduce CVD risk." (PMID 38522750, 2024). "However, it has not been reported whether lncRNA MALAT1 may participate in the pathogenesis of lower limb atherosclerosis in diabetes through NLRP3-mediated pyroptosis." (PMID 38439031, 2024). "Additionally, future research should also consider the interaction between Olfr2 and NLRP3, and whether alternative molecular pathways or additional mechanisms within the Olfr2 pathway might contribute to Corilagin’s atherosclerosis-mitigating effects." (PMID 38803504, 2024). "Thus, since several studies have confirmed that colchicine limits NLRP3 inflammasome activity, this drug might have a great potential role to limit atherosclerosis." (PMID 36768804, 2023). "More compellingly, researchers may further delve into the potential clinical value of affecting pathological changes in atherosclerosis by modulating the initial transcription immune response and intracellular multiprotein assembly process of the NLRP3 inflammasome." (PMID 37123477, 2023). "However, the regulation of NLRP3 inflammasomes activation and pyroptosis in macrophage during atherosclerosis are largely unknown." (PMID 36229750, 2023). "Isoliquiritigenin, a licorice extract, attenuated TNF-α-induced NLRP3 inflammasome activation and pyroptosis in human umbilical vein endothelial cells by targeting sirtuin-6, which could be beneficial in the management of atherosclerosis." (PMID 37765019, 2023). "Thus, perhaps the discovery of clinically approved novel pharmacological molecular inhibitors of NLRP3, along with other adjuvant therapy agents, may bring new therapeutic strategies with a reduced burden of atherosclerosis complications." (PMID 37175869, 2023). "Also in this model, Nlrp3 deficiency results in significantly smaller atherosclerotic lesions compared to WT animals, highlighting the importance of both the NLRP3 inflammasome in the pathogenesis of atherosclerosis and of the dietary intake as subordinate activation signal." (PMID 37239938, 2023).